TNF (tumor necrosis factor)
Diseases named in the same sentence as TNF in open-access papers (continued):
Sharing a sentence is not in itself a finding about the gene and the disease.
Obesity (continued). "Obesity causes lipid accumulation in adipocytes, which activates c-Jun N-terminal kinase (JNK) and nuclear factor-kappa B (NF-κB) signaling pathways and might subsequently increase the production of proinflammatory cytokines such as tumor necrosis factor-alpha (TNF-α) and interleukin-6 (IL-6)." (PMID 26136779, 2015). "Although the mechanism for reduced adiponectin during obesity and T2DM has been attributed, in part, to an increase in local TNF-α in adipose tissue, strain-related variability of adiponectin gene expression and plasma has been previously documented." (PMID 26146567, 2015). "The second factor was denoted the obesity-inflammatory domain, upon which BMI percentile, hs-CRP, TNF-α, and PAI-1 positively loaded." (PMID 26011530, 2015). "Conversely, women afflicted with PCOS endure a state of hyperandrogenism which results in increased adiposity, leptin, inflammatory markers TNFα and IL6, and obesity independent decreases in adiponectin." (PMID 26317527, 2015). "As SFRP5 does reduce production of proinflammatory TNFα, IL-6, and MCP-1, we expect it to exert anti-inflammatory effect in obesity related lung injury." (PMID 24899788, 2014). "The novel results of our study demonstrate that IUGR dysregulates the TNFα system and activates the UPR in an adipose depot and sex-specific manner prior to the onset of obesity and impaired glucose tolerance." (PMID 24804087, 2014). "We explored the relationship between age, eGFR, sex, obesity, LVH, hypertension, diabetes, smoking status, peripheral vascular disease or history of atrial fibrillation with TNFα, TNFR1, TNFR2 and IL-6 in the combined HF group." (PMID 24923671, 2014). "For example, the levels of circulating fibrinogen and other acute phase reactants, including TNF, IL-6, and C-reactive protein (CRP) were found to be elevated in obesity." (PMID 25309773, 2014). "Increased concentration and expression of tumor necrosis factor-α (TNF-α), interleukin-6 (IL-6), and monocyte chemoattractant protein-1 (MCP-1) are evident in adipocyte dysfunction and insulin resistance in obesity and metabolic syndrome." (PMID 24932457, 2014). "The effect of the carbimazole on expression of tumor necrosis factor (TNF-α) in liver, was investigated in an experimental model of high fat diet (HFD) induced obesity." (PMID 25258706, 2014). "However, high hypothalamic TNFα mRNA expression in these animals indicates a hypothalamic inflammatory process that could contribute to incomplete reversion of hyperphagia and development of late obesity." (PMID 25258479, 2014). "Depletion of CD8+ cells in obese mice decreased the number of macrophages in adipose tissue and lowered TNF-α and IL-6 levels, while T cell receptor (TCR)−/−mice were clearly protected against obesity-induced hyperglycemia and insulin resistance." (PMID 24823865, 2014). "In obesity, adipocytes can release pro-inflammatory mediators, such as quimiokine CC (CCL) -2, TNF-α and NEFAs instead of leptin and adiponectine that promote insulin sensitivity in a normal state." (PMID 25493077, 2014). "Serum levels of TNFα, MIP-1α, and MIP-1β, and classical markers of systemic inflammation of obesity were significantly greater in HFD than chow fed mice after 24 weeks, but not earlier." (PMID 25309539, 2014). "Furthermore, monocytic Fas expression in obese human individuals correlated positively with circulating TNFα concentration suggesting that the latter might be one of the downstream effectors of Fas up-regulation in myeloid cells in obesity-induced insulin resistance in human individuals." (PMID 24203314, 2014). "Obesity is proposed as a chronic low-grade proinflammatory state; alterations in CRP and proinflammatory cytokines such as TNF-α and IL-6 are commonly reported in obesity." (PMID 23826157, 2013).
Obesity (continued). "Analysis of hormones and cytokines related to the development of obesity and hepatic steatosis showed that both MSG-containing diet groups had significantly higher levels of serum leptin and TNFα (MSG + TFA and ASP + MSG + TFA diet mice, P <0.05)." (PMID 23783067, 2013). "Weight gain during the course of obesity induces low grade chronic inflammation in white adipose tissue (WAT) and liver leading to the release of pro-inflammatory cytokines such as TNF-α into circulation." (PMID 23349837, 2013). "An increase in plasma PAI-1 levels observed in obesity can also be the result of a cytokine-dependent induction of PAI-1 transcription where the proinflammatory cytokines such as IL-1, IL-6, and TNFα play the major role." (PMID 23819014, 2013). "Here, our results show that obesity increased hypoxic (HIF-1α) and inflammatory responses (TNF-α and NF-κB) in the cochlea of CD/1 mice, especially in the SG and SL." (PMID 23637762, 2013). "Waist circumference, the clinically accepted measure of obesity was significantly correlated with FPG, Insulin, IR, TBARS and TNF-α." (PMID 22860025, 2012). "TNF-α enhances the expression of PAI-1 in human adipose tissue and plasma PAI-1 levels in obesity subjects and is responsible for reduced fibrinolysis and also a component of extracellular matrix, leading to renal fibrosis and terminal renal failure." (PMID 22567283, 2012). "The physiological source of increased circulating levels of TNFα in T2D remains unclear; however it is believed to be a major cytokine involved in the exchange between adipose tissue and muscle with increased levels in obesity and T2D possibly contributing to IR in skeletal muscle." (PMID 23144726, 2012). "On the other hand, adipocyte hypertrophy with the development of obesity, subsequently resulting in secretion abnormalities of FFA and adipocytokines such as TNF-α and IL-6, which are involved in insulin resistance." (PMID 22348333, 2012). "Recent data have revealed that the plasma concentrations of inflammatory mediators, such as TNF-α, MCP-1 and IL-6, are increased in the insulin resistant states of obesity." (PMID 21589925, 2011). "Increased levels of activated plasminogen activator inhibitor 1 (aPAI-1), tumor necrosis factor-alpha (TNFα), C-reactive protein (CRP), as well as other conditions such as obesity and the MetS, are now considered low-grade inflammatory states." (PMID 21483749, 2011). "Obesity reflects ageneralized proinflammatory state with its increased inflammatorymarkers like C reactive protein, IL-6, IL-8, IL-10, PAI-1,TNF-α, and hepatocyte growth factor." (PMID 21991518, 2011). "Obesity isassociated with increased SUA levels and overproduction ofinflammatory molecules like TNF- α and IL-6 by the white adipose tissue." (PMID 21625475, 2011). "AP also reduced hyperglycemia and hyperinsulinemia by increasing adiponectin secretion and suppressing TNF-α secretion by white adipocytes, and elevating the expression of GLUT4 in skeletal muscle in addition to reducing obesity." (PMID 21799697, 2011). "The seminal finding that the expression of a proinflammatory cytokine, tumor necrosis factor-α (TNF-α), is elevated in the adipose tissue of obese mice provided the first evidence of a link between obesity and inflammation." (PMID 21676245, 2011). "Several studies evidenced an increased TNF-α circulating level both in obese nondiabetic subjects and in type 2 diabetic patients and hypothesized its involvement in the pathogenesis of obesity-linked insulin resistance." (PMID 20652043, 2010). "Most of the remaining 21 are inflammatory proteins such as IL-8, PAI-1, MCP-1, IL-6, IL-1Ra, TNFα, sTNF RII, and IL-18 but the source of the elevated circulating levels in obesity is unclear." (PMID 20508843, 2010). "Many obesity-related factors are responsible, including increased blood levels of insulin/IGF, IL-6, TNF-alpha, and leptin, and decreased blood levels of adiponectin." (PMID 21103795, 2010).
Obesity (continued). "In addition, evidence suggests that the increase in systemic TNF-α in obesity is derived from these adipose macrophages, which suggests that this increase in infiltrated macrophages might represent the cause or consequence of the low-grade inflammation observed in obesity." (PMID 20877574, 2010). "Here, we have obtained clear evidence that endurance exercise and CR led to potent suppression of pro-inflammatory cytokines including osteopontin, TNF-α, MCP-1 and IL-6, all of which have been shown to be elevated in the state of obesity and type 2 diabetes." (PMID 20633301, 2010). "In obesity, JNK activity is increased in the liver, muscle, and fat tissues probably due to the increase of free fatty acids and TNF-α." (PMID 20508722, 2010). "In summary, the present study demonstrated relationships between obesity, adipose tissue inflammation reflected by increased adipose tissue expressions of CD68 and TNF-α, and insulin resistance in patients with COPD." (PMID 21197447, 2010). "In conclusion, we found that high plasma calprotectin levels were a marker of obesity independently of classical inflammation markers such as CRP, TNF-α and circulating neutrophil number." (PMID 19823685, 2009). "In the present study,we examined whether resistin TNF-α, IL-6, and IL-1β mRNA levels from human peripheral mononuclearcells are altered in type 2 diabetes and whether they correlate withcirculating resistin levels and with indices of obesity or insulin resistance." (PMID 19125180, 2008). "RT-qPCR results showed that, compared with the control group, mRNA expression levels of VEGFA, VEGFR-2, CD31, and SIRT1 were significantly decreased in the obesity group (P < 0.001), while the expression levels of GLUT1, HIF-1α, TNF-α, IL-6, HMGB1, and TLR4 were significantly upregulated (P < 0.01)." (PMID 41505418, 2026). "A meta-analysis pooling data from four studies yielded a combined SMD of −0.387 (95% CI: −7.78 to 0.03; τ2 = 15.40, p = 0.052), indicating that HIT was not effective in reducing TNF-α levels in children with obesity." (PMID 41590696, 2026). "In vitro studies have confirmed that betaine can inhibit the expression of hypoxia-induced IL-6 and tumor necrosis factor-alpha (TNF-α) mRNAs in human adipocytes, indicating that it directly acts on adipose tissue to reduce obesity-related low-grade inflammation." (PMID 41608511, 2026). "Higher IL-1β, IL-6, IFN-γ and TNF-α levels were observed in the subgroups with obesity than in the normal weight subgroups, regardless of gender." (PMID 41602164, 2026). "In patients with obesity, elevated blood levels of high‐sensitivity C‐reactive protein (hs‐CRP), tumor necrosis factor (TNF), and interleukin 6 (IL‐6) may increase local inflammation in periodontal tissues, thereby accelerating disease progression." (PMID 40955131, 2026). "Interestingly, in the older men subgroup with obesity and high CMI, the pattern shifts towards a more clearly atherogenic, Th1-oriented profile, with TNF-α and IFN-γ emerging as the main predictors of CMI." (PMID 41602164, 2026). "Interestingly, TNF-α levels declined across disease stages, possibly reflecting subclinical inflammation in Ecuadorian NDC with high rates of obesity and dyslipidemia." (PMID 41150807, 2025). "Furthermore, Ang 1–7 reduced MCP-1 and TNF-α secretions in 3T3-L1 white adipocytes and RAW 264.7 macrophages, respectively, which are in vitro experimental models mimicking obesity condition." (PMID 39803918, 2025). "We determined the circulating concentrations of adiponectin, leptin, resistin, TNFα, and IL-6 in participants with obesity and type 2 diabetes with and without obesity, and compared them to those of the control group." (PMID 40095937, 2025). "Sixth, This study only examined the relationship between IL-6, TNF-α, and IL-2 levels and psychiatric symptoms and obesity, without testing other factors, particularly C-reactive protein (CRP) and interleukin-10 (IL-10)." (PMID 40791199, 2025).
Obesity (continued). "Additionally, we focused on the potential effects of these dietary regimens on the expression of the obesity-related gene FTO, and the inflammatory biomarker TNF-α in the prostate tissue." (PMID 40481981, 2025). "In individuals with obesity and related pathologies, resveratrol supplementation at doses of 500 mg/day or higher for over 12 weeks has been shown to reduce inflammatory markers like C-reactive protein (CRP) and TNF-α, alongside a decrease in BMI." (PMID 40943464, 2025). "Although anti–TNF-α therapies are highly effective in rheumatoid arthritis, they have consistently failed to improve glycemic control or body weight in obesity and type 2 diabetes." (PMID 41463063, 2025). "Studies reveal that Acrp30 levels are diminished in various obesity and diabetes models due to elevated TNF-α levels, indicating a negative correlation between this protein and diabetes." (PMID 40141412, 2025). "Notably, IL-6, IL-8, AEA, OEA, MMP-2, and TNF-α were elevated in individuals with MUO and also correlated positively with BMI, further reinforcing the link between chronic inflammation and obesity." (PMID 40153192, 2025). "Some studies suggest that a lower n-6:n-3 ratio may improve metabolic parameters in adolescents with obesity and fatty liver disease, enhance glucose and lipid metabolism in T2DM, and decrease serum levels of TNF-α, IL-1β, IL-6, and MCP-1." (PMID 40573106, 2025). "Despite the well-known connection between obesity and chronic subclinical inflammation, we did not observe a significant reduction in the studied inflammatory markers (ferritin, IL-6, TNF- α resistin, PAI-1) following the treatment with submaximal GLP-1 RA." (PMID 41011232, 2025). "In obesity, adipose tissue generates large amounts of pro‐inflammatory mediators, including leptin, resistin, retinol‐binding protein 4 (RBP4), lipocalin 2, and cytokines such as IL‐6, IL‐1β, and TNF‐α." (PMID 40673471, 2025). "Similarly, tumor necrosis factor (TNF)-α and IL-6 are elevated in the colonic mucosa of individuals with obesity, activating procarcinogenic pathways like NF-κB and ERK 1/2, which promote cell proliferation and survival." (PMID 40722646, 2025). "Additionally, it has been described that obesity elevates the acetylation of H3K9 and H3K18 lysine residues in TNF gene." (PMID 40265287, 2025). "Studies have shown that OSA patients demonstrate higher levels of inflammatory factors (CRP, fibrinogen, TNF-α, IL-6), regardless of obesity status." (PMID 40428013, 2025). "Inflammatory cytokines, such as tumor necrosis factor (TNF) and interleukin‐6 (IL‐6), can disrupt the normal balance of energy metabolism and lead to insulin resistance, which can further promote weight gain and obesity." (PMID 39652453, 2025). "Moreover, obesity suppresses the expression of IFN-γ, IFN-β, TNF, and granzyme B (GzmB) in CD8 T cells." (PMID 40863244, 2025). "Moreover, the upregulation of ADAM17, frequently observed in obesity, promotes ACE2 shedding and TNF release, further aggravating inflammation." (PMID 41562075, 2025). "By contrast, the positive association between CAMKK1 and TNFα was strengthened in patients with T2DM, but not individuals with obesity." (PMID 40965347, 2025). "Therefore, the aim of this secondary analysis was to compare the effects of TRE versus CR on key inflammatory markers (TNF-alpha, IL-6, and CRP) in adults with obesity over 12 months." (PMID 40218888, 2025). "Obesity-induced chronic inflammation triggers elevations in white blood cell (WBC) and monocyte (MO) counts, high-sensitivity C-reactive protein (hs-CRP), and inflammatory cytokines such as interleukin 1β (IL-1β), IL-6, and tumor necrosis factor α (TNFα)." (PMID 40432213, 2025). "Our meta-analysis supports these findings, demonstrating a significant TNF-α reduction with IRV during surgery, highlighting its dual benefits in improving respiratory mechanics and mitigating inflammation in patients with obesity undergoing laparoscopic procedures." (PMID 40142871, 2025).
Obesity (continued). "TNF-α levels are inversely correlated with insulin sensitivity, while IL-6 and IL-1β inhibit insulin receptor substrate 1 (IRS-1); moreover, elevated levels of leptin in women with pregestational obesity contribute to insulin resistance." (PMID 41374008, 2025). "As obesity develops, DUSP5 mRNA expression rises with an increase in TNFα expression." (PMID 40093618, 2025). "A similar trend was observed in this study, where obesity reduced the activities of oxidative stress enzymes SOD, CAT, and GSH‐PX, while increasing oxidative damage markers such as MDA and GSH, as well as inflammatory factors IL‐6 and TNF‐α." (PMID 40260060, 2025). "Anti-TNFα therapy reduced intestinal permeability, alleviated pancreatitis, and improved the expression of IGF2BP3 and CLDN11 in intestinal epithelial cells in experimental obesity-related SAP." (PMID 39856555, 2025). "When comparing the average cytokine levels among the groups, we found that the obesity class II‐III group showed a significantly higher expression of CCL2/MCP‐1 and TNF‐α, despite having a considerably lower cell count compared to the normal weight/overweight group." (PMID 40518865, 2025). "In fact, a rise in circulating ANGPTL2 levels bears a close association with C-reactive protein expression in obesity and an increase in expression of pro-inflammatory TNF-α and its receptor TNFR1 in the onset and progression of T2D, obesity, and heart failure." (PMID 40427505, 2025). "TNF-α, interleukin-6 (IL-6) and plasminogen activator inhibitor-1 (PAI-1) may regulate BP in obesity." (PMID 40761303, 2025). "Notably, diabetes and obesity are always accompanied by chronic low‐grade inflammation, but JTTZF significantly reduced pro‐inflammatory cytokines (IL‐1β, TNF‐α and IL‐6) in diabetic mouse livers." (PMID 41250907, 2025). "This is consistent with the findings in the current study, where TNF-α was a significant predictor of abdominal obesity but not general obesity." (PMID 40137151, 2025). "Inflammation of the adipose tissue is mediated by inflammatory cytokines, such as IL1-1β, IL-6, IL-8, IL-10, IL-12, and Tumor Necrosis Factor (TNF-α), as well as chemokines including MCP-1, which are produced by M1 macrophages in the adipose tissue of individuals with obesity." (PMID 38396489, 2024). "After infection, the results of IFN-γ, TNF-α, IL-4, IL-10 and IL-12 p70 in obesity + infection group were not obviously different from those in normal + infection group." (PMID 38185681, 2024). "The interaction analysis showed that combination of both asthma and obesity had significant effects on IL-5, IL-10, IL-17A, IL-33, TNF-α, and leptin, but the effects were not synergistic or additive." (PMID 39902293, 2024). "Women with PCOS exhibit elevated serum concentrations of TNF and C-reactive protein (CRP), along with increased levels of monocytes and lymphocytes, and obesity and hyperinsulinemia could further exacerbate the chronic inflammatory condition." (PMID 38978626, 2024). "No statistical differences were found in IL-6 and TNF-α between groups of children with obesity vs. those of normal weight or in children with vs. those without MetS." (PMID 39771030, 2024). "Increased TNF-α levels were positively correlated with BMI, WHR, NC, glucose, TC, TG, LDL-C, VLDL, SBP, and DBP, indicating a strong link between TNF-α and metabolic and cardiovascular parameters commonly affected by obesity and metabolic syndrome." (PMID 39149648, 2024). "Also the up-regulation of TNF-α levels in the brains of mice fed with HFD, confirms neuroinflammation in the diet-induced obesity in animal model." (PMID 39281480, 2024). "We found that leukocyte and neutrophil counts were slightly higher in children with obesity but levels of IL‐1β and TNF‐α were not statistically significant." (PMID 40626250, 2024). "Interestingly, the number of CD9-positive particles of subjects with obesity positively correlated with BMI, as well as SAT TNF expression levels." (PMID 38965596, 2024).